TNF (tumor necrosis factor)
Diseases named in the same sentence as TNF in open-access papers (continued):
Sharing a sentence is not in itself a finding about the gene and the disease.
tumor (continued). "Treatment of NF-κB inhibitor in PC3-M and C4–2B-M cells blocked the expression of these cytokines and chemokines, suggesting TNF-α-mediated NF-κB activation is essential for PCa cells to alter the tumor environment and promote the advancement of PCa." (PMID 37867861, 2023). "Cytokines, such as IL-1β and TNFα, are primarily pro-inflammatory and play an important role in inflammation-driven tumor growth and progression and are found to be upregulated after radiotherapy in patients with GBM." (PMID 38003396, 2023). "Induction of the canonical NF-κB pathway is initiated by pattern recognition receptors and diverse tumour-promoting cytokines, such as TNF, IL-1, and IL-17." (PMID 36899924, 2023). "Increased TNF-α in the tumour microenvironment has been demonstrated to favour invasion through promotion of pro-inflammatory, pro-invasive phenotypes of OSCC cells and paracrine mechanism mediated recruitment and activation of inflammatory cells." (PMID 36980727, 2023). "N2-type TANs support tumor growth and convert TANs to antitumor N1-type neutrophils by blocking TNF-α or boosting IFN." (PMID 37108109, 2023). "ACM derived from OGJ patients with early-stage tumours had significantly increased levels of pro-inflammatory TNF-α compared with ACM derived from OGJ patients with late-stage tumours (early-stage: 2,730 ± 1,412 vs. late-stage: 806.1 ± 131.8 pg/gram p = 0.05)." (PMID 36790524, 2023). "Recently, it has been described that systemic administration of TNF-expressing tumor cells can reduce tumor growth and metastatic colonies in immunocompetent mice." (PMID 37112810, 2023). "The release of cytokines IL-1β, IL-6, IL-8, and TNF-α was analyzed in the supernatants of tumor cells (24 h) and CD34+ HSCPs (24, 48, 72 h) after IR (single-dose: 9 Gy) in order to investigate the influence of IEPA on inflammatory responses." (PMID 36903253, 2023). "NFR1-dependent TNF signaling has been reported to impair the accumulation of tumor-infiltrating lymphocyte (TILs) and induce significant death of activated CD8+ T cells." (PMID 38149248, 2023). "We examined the expression of granzyme B, interferon (IFN)-γ, and tumor necrosis factor (TNF)-α all of which play a major role in cell contact-independent tumor cell killing." (PMID 37100864, 2023). "These macrophages exhibit potent anti-tumor effects by releasing pro-inflammatory cytokines (such as TNF and interleukin (IL)-2) and active nitrogen and oxygen intermediates." (PMID 37512096, 2023). "We also evaluated variation in the levels of inflammatory factors such as amylase (AMY), TNF-α, and IL-1β in the blood of tumor-bearing mice after different treatments." (PMID 37649601, 2023). "After hypoxia treatment, circPRDM4 depletion alleviated tumor cell-mediated immune suppression, as determined by the elevated levels of secreted TNF-α and IFN-γ from cocultured T cells." (PMID 36747292, 2023). "The mRNA levels of proinflammatory/pro‐tumour cytokines were measured by qRT‐PCR, and the induction of TNF‐α and Ltβ strikingly correlated with tumour development in the CLI Fah−/− mice." (PMID 37997519, 2023). "GSVA analysis showed that clusters 5 and 6 were mainly enriched in pathways regulating the tumor microenvironment, such as oxidative phosphorylation, TNF-α signaling via NF-Kβ, and endothelial-mesenchymal transition." (PMID 37144239, 2023). "The observed increase in pro-inflammatory cytokines, such as IFN-γ and TNF-α, further supports the notion that ProLNG-001 fosters an immune stimulatory environment, thereby enhancing anti-tumor immune responses and promoting tumor regression." (PMID 37766179, 2023). "Tumor-derived gangliosides inhibit anti-tumor efficacy via altering TNF-induced NF-κB activation in T cells and inducing T cell apoptosis." (PMID 37190141, 2023). "Apart from this, JNK has activated the inflammatory lung environment to support tumor development by regulating cytokines including IL-1β and TNF-α." (PMID 37259369, 2023).
tumor (continued). "Recently, a single-cell study on MCs in pan-cancer classified tumor MCs into two subtypes: anti-tumorigenic MCs, which are characterized by a high TNF/VEGFA expression ratio, and pro-tumorigenic MCs, which are characterized by a low TNF/VEGFA expression ratio." (PMID 38031173, 2023). "Pro-inflammatory cytokines, such as Interleukin (IL)-1, IL-6 and tumor-necrosis factor (TNF)-α, and the expression of inflammatory chemokines (i.e., CXCL9 and CXCL10) has been associated with RCC tumor growth, angiogenesis, and response to therapy." (PMID 36672355, 2023). "CXCR2 ligands, including CXCL5, CXCL2, and CXCL1, produced by TNF-α activated MSCs account for the deposition of neutrophils at tumor primary sites and contribute to the metastatic microenvironment formation." (PMID 38022534, 2023). "Transplanted tumours become more vulnerable when TNF-α was first recognized to have a function in hemorrhagic necrosis." (PMID 35813433, 2022). "To this end, we measured the cytokines IL-1, IL-10, and TNF-α produced by these tumor-conditioned macrophages." (PMID 36686704, 2022). "We subsequently analyzed the influence of the anatomical tumor localization on concentrations of CgA, the NETest, as well as IL-1β, IL-6, IL-8, IL-10, IL-18, and TNF." (PMID 36294509, 2022). "Further, nuclear transcription factor-κB (NF-κB), a key factor in inflammation and tumor cells, induces TNF-α and IL-6 chemotactic leukocytes to infiltrate the inflammation site." (PMID 36406359, 2022). "Necroptosis can promote tumor progression by activating an inflammatory response, while elevated TNF-α expression in the TME is characteristic of many malignancies and associated with poor prognosis." (PMID 35795676, 2022). "We found reduced tumor-resident TNF-α+ B cell populations compared to matched blood, and TNF-α+ TIL-B engaging in extensive crosstalk with Tregs, likely supporting immune cell suppressive activities in the TME." (PMID 35909944, 2022). "This illustrates that the combination therapy had the most significant effect on reducing the TNF-α tumor tissue." (PMID 35798765, 2022). "The authors found that low-dose NTX reduces CRC tumor size by increasing M1 macrophages and tumor necrosis factor-α (TNF-α)." (PMID 35648340, 2022). "The TNF-α levels of plasma (65.8% vs Ctrl) and tumor (66.9% vs Ctrl) were significantly decreased by NOB." (PMID 35440077, 2022). "Inflammatory cells are also present in the TME, where they modulate tumor growth by the secretion of active molecules (such as IL-1β, IL-33, IL-6, TNF-α, and IL-17) into the TME." (PMID 36588722, 2022). "These cells can directly induce tumor apoptosis via granzyme B (CTLs only) and production of IFNγ and TNFα, two cytokines which broadly reprogram the TME and can induce apoptosis in tumor cells." (PMID 35406557, 2022). "STX6 was primarily implicated in tumor growth through the microRNA, MAPK, and TNF signaling pathways." (PMID 36612024, 2022). "For example, the addition of TNFα/TNFRs inhibitors to the blockade of PD-L1/PD-1 has potentiated anti-tumor effects in animal cancer models." (PMID 35884574, 2022). "Tumor cells induce various inflammatory cytokines, including TNF-α, IL-1β, IL-6, IL-17/18, and IL-23, and growth factors (G-CSF, GM-CSF, and IL-3) to generate neutrophil production and confirm their survival." (PMID 36091114, 2022). "Among which, the expressions of anti-tumor cytokines including IL-2, IL-15 IL-17A, IFN-γ and TNF-α were up-regulated, while tumor-promoting cytokines including IL-4 and IL-10 were down-regulated in HER2.28ζ/PD-L1.BB CAR-T cells." (PMID 36402752, 2022).
tumor (continued). "Inflammatory cells can change the tumor microenvironment through overproducing cytokines, including IL-2, IL-6, and TNF-α, thus promoting tumorigenesis and the proliferation, migration, and immune escape of tumor cells." (PMID 35872847, 2022). "Tumor-secreted factors, such as IL-6 and TNF-α, have been proposed to inhibit lipogenesis and/or to promote lipolysis." (PMID 35319749, 2022). "It was reported that triptolide (TPL) sensitized tumor cells to TNF-α-induced apoptosis by blocking TNF-α-induced activation of NF-κB and transcription of c-IAP1 and c-IAP2." (PMID 36308574, 2022). "Varied studies have also shown that luteolin blocks the expression of MMPs, pro-inflammatory cytokines such as TNF-α (tumor necrosis factor), IL-6 (interleukin), IL-1, NF-κB, and endothelial migration, the factors involved in tumor progression and metastasis." (PMID 36358791, 2022). "TNF-α, found in the tumor-bearing rats, raises corticotrophin-releasing hormone (CRH) and lowers food consumption." (PMID 35159388, 2022). "Concomitant events include the secretion of tumor-promoting pro-inflammatory cytokines (IL-6, TNFα and IL23) and the production of immune suppressive factors (e.g., Arg1, TGFβ, and IDO)." (PMID 35237269, 2022). "We have previously demonstrated that directing TNFα-CSG to tumor ECM triggers immune cell infiltration which in turn delivers a cocktail of ECM-degrading proteases leading to specific tumor ECM breakdown." (PMID 35273916, 2022). "Mechanism studies have discovered that MSCs reduced and increased the concentrations of tumor‐promoting factors such as IL‐1 and TNF‐α, and tumor suppressor IL‐10 respectively." (PMID 34981659, 2022). "NK cells can destroy tumor cells by secreting TNF-α and tumor necrosis factor-related apoptosis-inducing ligand, or cytokines, which are capable of reducing tumor cell proliferation and accelerating the inflammatory response, such as IFN-γ." (PMID 36246916, 2022). "These MMPs promote vascular and tumoral invasion as well as release tumour necrosis factor-alpha (TNF-α) and soluble Fas ligand which inhibits tumour cell apoptosis." (PMID 36045675, 2022). "Activated neutrophils increased GLUT type 3 and 4 expression resulting in increased glucose uptake, and tumor necrosis factor-α secreted by macrophages increased FDG uptake in tumor cells." (PMID 35517712, 2022). "Many osteoclast-activating factors (IL-6, IL-1β, HGF and TNF-α) are released by the mutual interactions of tumour and bone marrow cells with a major involvement of RANKL, the decoy receptor OPG, and MIP-1α a." (PMID 36362718, 2022). "Regarding differences between direct and indirect co-cultures, it is well-known that there are significant differences regarding interleukins, cell–cell adhesion and tumor necrosis factor alpha levels, which can influence the behaviour of tumor cells." (PMID 36098901, 2022). "The activation of M1 macrophages is beneficial to patients because it can induce acute inflammation secreting tumor-killing molecules such as tumor necrosis factor α (TNFα)." (PMID 35449571, 2022). "We found that necrotic tumor cells significantly promoted the expression of the proinflammatory factors TNFα, IFNβ, and IL1β in BMDMs from WT and L/L mice." (PMID 36224346, 2022). "Apigenin treatment produced stronger activation of anti-tumor CD8+ cytotoxic cells and greater production of anti-tumor cytokines IFNγ, TNFα, and granzyme B in the blood than luteolin." (PMID 36555392, 2022). "As a result, inflammatory cytokines are released from the inflammatory cells (TNF-α, IL-1β, IL-6, IL-8, etc.), promoting tumor invasion and progression." (PMID 35054779, 2022). "Driven by memory B cells and a range of cytokines (including TNF, IL-2, IL-6, and IFNγ), T cells home to the tumor bed and release perforin and granzyme or Fas/FasL pathways to destroy tumor cells." (PMID 36704336, 2022).
tumor (continued). "TNF-α is shown to be ectopically produced by malignant/leukemic and immune cells in the tumor microenvironment, providing a tumor-supportive atmosphere and playing a significant role in the establishment and progression of malignant disease." (PMID 35547942, 2022). "In line with this, FACS analysis of expression of IL-2, IFNγ and TNF-α expression in T cells through intracellular staining revealed that combination therapy resulted in increased effector function of tumor-infiltrating CD8 + T cells." (PMID 36457047, 2022). "Among them, CD8+ T cells infiltrate tumors as a symbol of immune recognition and destroy tumor cells by secreting granzyme B, TNF, and IFNγ, indicating better survival in OC patients." (PMID 35837397, 2022). "Upon incubation with anti-KIR2DL5 blocking mAb F8B30, KIR2DL5+ NK cells manifested more potent cytotoxicity, degranulation (CD107a), and functional cytokine (IFN-γ and TNF-α) production after coculturing with PVR+ A427 or Jurkat tumor cells." (PMID 36377656, 2022). "A possible mechanism is as follows: cytokines such as tumor necrosis factor and interleukin 6 are produced by tumor cells or surrounding cells and promote protein degradation and decreased synthesis." (PMID 35463384, 2022). "R848 delivered by complement C3-targeted liposomes triggered various signal cascades to increase the expression of cytokines and factors (such as TNF-α, IL-1β, IL-6 and IL-12), leading to the delay of tumor growth in 4T1 tumor-bearing mice." (PMID 35413927, 2022). "Then, we showed that CBX7 inactivated the TNF signaling pathway to inhibit tumor proliferation and enhanced the sensitivity of ccRCC cells to TKIs." (PMID 35342353, 2022). "Tumor vasculature is predominantly leaky due to proteolytic degradation, remodeling/angiogenesis, paracrine signaling (such as the secretion of tumor necrosis factor (TNF)α) and hypoxia which disrupt the normal function of endothelial cells." (PMID 36158191, 2022). "The antitumor effect of NK cells is induced by secreting several killer cytokines (e.g., IFN-γ and TNF-α) and chemokines and by inducing tumor cell apoptosis via the Fas/FasL pathway as well as the release of cytotoxic granules (mainly perforin and granzyme)." (PMID 35757756, 2022). "TNF-α enhances NFκB signaling and, subsequently, stimulates inflammation, tumorigenesis, and proliferation, and increases the survival of pre-tumor cells." (PMID 35410210, 2022). "Gene microarray of tumor cells suggests a dependence on TNF and TGFβ signaling pathways leading to apoptosis." (PMID 35574362, 2022). "One inflammatory cytokine which has been linked to pro-tumor effects is the tissue necrosis factor α (TNF-α) when produced in the tumor microenvironment." (PMID 34480199, 2022). "Actually, in the inflammatory tumor microenvironment of TNBC, TNF-α has been proved to be a major factor that triggers tumor cell immunosuppression against T-cell surveillance." (PMID 34875483, 2022). "In the present study, we also investigated the expression profile of tumor immunoregulatory genes TNF-α, TGF-β, IL-10, and iNOS in macrophages conditioned with OSCC tumoral media treated with PL during polarization." (PMID 36686704, 2022). "Inflammatory cytokines such as IL-1β, TNFα, and IFNγ are produced to combat the initial tumor via activation of NF-κB, STAT1, and NLRP3 inflammasome pathways." (PMID 36555392, 2022). "Both IL-6 and TNF-α were also increased in the tumour-bearing SID mice compared to the tumour-bearing mice without intercurrent surgery." (PMID 36010845, 2022). "Another study extended the concept by showing the role played by TNF in promoting activation-induced cell death (AICD) of CD8+ tumor-infiltrating lymphocytes (TILs) upon anti-PD-1 and anti-CTLA-4 combination therapy in mice." (PMID 36016934, 2022). "Tumor cells, as well as host immune cells, contribute to this inflammatory state by releasing pro-cachectic cytokines such as TNFα, IL-1, IL-6, and IFN-γ." (PMID 35740519, 2022).
tumor (continued). "M1-type TAMs produce anti-tumor factors TNF-α and NO, stimulate T cells to induce activation and play an anti-tumor immune response." (PMID 35965533, 2022). "Then, exogeneous GABA was introduced in B cell knockout mice and it significantly downregulated the gene transcription profiles related to inflammatory cytokines such as TNF and interferon-γ (IFN-γ) in tumor-associated macrophages." (PMID 35915062, 2022). "TNF-α is also critical in the creation of a tumor microenvironment and aids malignant cells in immune evasion, survival, and treatment resistance." (PMID 35547942, 2022). "TNF-α promotes tumor cell survival and treatment resistance in AML by upregulating heme oxygenase-1 (HO-1) without activating nuclear factor kappa B (NF-KB)." (PMID 35547942, 2022). "TNF and other inflammatory cytokines that are produced by macrophages in the tumor microenvironment stimulate tumor cells to produce IL-6 and LIF, contributing to tumor growth." (PMID 35740622, 2022). "A combination of the anti-PD-1 antibody and the designed nanovaccine was used to inhibit the tumor immune escape and increase tumoricidal activity by enhancing tumor-specific T cell infiltration and the release of TNF-α in the TME." (PMID 36010836, 2022). "In another study, IL-10 as an anti-inflammatory cytokine was significantly increased, whereas Tumor necrosis factors TNF-α and IL-6 decreased following calorie restriction." (PMID 36364892, 2022). "Our prior work identified a paracrine inflammatory loop in breast cancers that disrupts the microenvironment of both the tumor and surrounding myeloid cells and involves TNF-α, CXCL1/2, and S100A85." (PMID 36241629, 2022). "Other than being one of the major proinflammatory cytokines, TNFα acts as a mediator of cancer-related inflammation in the tumor microenvironment." (PMID 36290384, 2022). "For example, cancer cells secrete tumour-promoting cytokines such as IL-6, TNF-α, and IL-1 which – along with potentiating their own growth and survival – leads to the recruitment of immunosuppressive immune cells to the tumour microenvironment." (PMID 35359426, 2022). "In 2018, Zhigang Tian lab found that the blockade of TIGIT reversed the exhaustion of tumor-infiltrating NK cells, increased the frequency of tumor-infiltrating NK cells expressing CD107a, tumor necrosis factor, interferon-γ, and CD226." (PMID 36289396, 2022). "Regarding the ADP@SWNT/TNFα+irradiation group, since laser irradiation at 808 nm was applied at day 19, the tumor size was similar to that of the ADP@SWNT/TNFα alone group during the first 18 days." (PMID 34994069, 2022). "At 24 h post-infection, the neutrophils isolated from the OrfV- or PBS-treated mice were incubated with TNF-α-neutralizing antibodies prior to co-culture with the target tumor cells." (PMID 36139433, 2022). "In one study of lung cancer, researchers found that the recruitment of MDSCs decreased in TNF KO mice compared with WT mice, inhibiting tumor growth." (PMID 36358977, 2022). "The high ranking enriched pathways involved pathways of neurodegenerative multiple disease, MAPK signaling pathway, HIF-1 signaling pathway, TNF signaling pathway, and various infection and tumor-specific pathways." (PMID 36110545, 2022). "Senescent T cells are also able to produce inflammatory cytokines (IFN-γ and TNF-α) to modulate the tumor microenvironment." (PMID 35875098, 2022). "PLCL1, as a survival-related gene of GC, is also significantly correlated with clinical characteristics, tumor microenvironment immune cells, tumor mutation burden (TMB), and tumor necrosis factor (TNF)." (PMID 35912206, 2022). "Alternatively, the Co treatment, alone or with A, resulted in much lower frequency of CD4+ or CD8+ T cells with TNFα, and even more so IFNγ production in the tumor (CD4+ IFNγTNFα+: Co/A=17.2 ± 3.1, Ca/N=31.8 ± 4.1, p=0.0097)." (PMID 36419897, 2022).